CD4 (CD4 molecule)
Diseases named in the same sentence as CD4 in open-access papers (continued):
Sharing a sentence is not in itself a finding about the gene and the disease.
infection (continued). "We also captured the stage of infection (CD4lowp24low) where CD4 is already downmodulated while env mRNA and p24 are not fully expressed." (PMID 39373535, 2024). "Since both, hepatic NS3+ and NS4+ cells were detectable at sufficient numbers at day 21 pi (time point of clearance), we chose this time point to compare CD8+ T cells from mice depleted of CD4+ T cells 4 days prior to infection and non-depleted controls." (PMID 39392861, 2024). "Furthermore, in vitro infection of DCs with distinct TBEV strains results in distinct functional capacities, impacting later activation of CD4+ T cells." (PMID 38318179, 2024). "However, CD4 and CD8 T cell infiltration, which peaks at approximately 10−12 p.i., is needed to resolve productive infection in the brain." (PMID 39134803, 2024). "Cytokines produced by CD8+ and CD4+ T cells were dominated by either IFN-γ or IL-4, with the antiviral role of IFN-γ being well reported, but IL-4 produced by T cells also promotes a more rapid neutralizing antibody response to heterologous infections." (PMID 39340038, 2024). "However, in infected groups, compared with the normal + infection group, the proportions of CD3+CD279+ and CD3+CD4+CD279+ T cells were decreased in two undernutrition infected groups." (PMID 38185681, 2024). "Taken together, both CD4+ and CD8+ TRM cells have been shown to contribute to protection against a variety of viral infections, including HSV-1, HSV-2, LCMV, MCMV, IAV, and VACV, particularly at the site of infection." (PMID 39193473, 2024). "Much of our knowledge of memory CD4 T cell dynamics derives from studies of laboratory mice housed in specific pathogen-free conditions who have not experienced overt infections, but nevertheless have abundant memory phenotype (MP) CD4 T cells." (PMID 38948729, 2024). "We tested three cases: patients with i) varying levels of CD4 and CD8 immune cell activation, ii) varying levels of pro-inflammatory cytokine production, and iii) varying tendency for thrombus formation in response to infection and immune activation." (PMID 38820409, 2024). "SARS2-specific IFN-γ+ CD4+ and CD8+ T cell frequencies remained stable from study days 0 to 28, suggesting that antigen-specific, IFN-γ–producing T cells are formed early during primary infection and stably maintained at least through early convalescence." (PMID 39704169, 2024). "Furthermore, infection of primary CD4 + T cells with wild-type HIV-1 virus recapitulated many of the gene expression changes observed upon CPSF6 knock-out, while infection with an N74D capsid mutant virus recapitulated fewer of these changes." (PMID 39678349, 2024). "To test this, we analyzed ex vivo cytokine production in CD4+ T cells purified from the mesenteric lymph nodes of CBA mice 8 weeks post-infection, with or without RI neutralization." (PMID 39661861, 2024). "Importantly, these Th17 cells are primary target cells for HIV, expressing HIV coreceptors (CD4, α4β7, CCR5, and CXCR4), and thus play an important role in disseminating HIV during the acute phase of infection." (PMID 39352750, 2024). "To further expand our understanding of how Bhlhe40 regulates anti-Chlamydia immunity, we performed 5’ single-cell RNA sequencing (scRNAseq) and TCR profiling on activated CD4 T cells (CD44hi) sorted from WT and Bhlhe40-/- mouse FRT 14 days post intravaginal infection." (PMID 38271477, 2024). "Although primary infection with parasites, including Plasmodium berghei ANKA, followed by chloroquine treatment generates CD4+ and CD8+ TRM in the brain tissue of mice, it remains unclear whether these TRM cells are protective against reinfection." (PMID 39193473, 2024). "We show that CD4 and CD8 T cells efficiently eliminate M. tuberculosis infection in alveolar macrophages, but they have less impact on suppressing infection in MDM, which may be a bacterial niche." (PMID 38977711, 2024). "Indeed, in this infection, an increase in Ag-experienced IFN-γ-producing CD4+ T cells has been described." (PMID 38674719, 2024).
infection (continued). "Much of our knowledge of memory CD4 T cell dynamics derives from studies of laboratory mice housed in specific pathogen-free conditions, which have not experienced overt infections, but nevertheless have abundant memory phenotype (MP) CD4 T cells." (PMID 39137219, 2024). "Viral‐specific AIM + CD4 and CD8 T‐cells have been detected after vaccination and infection." (PMID 39659018, 2024). "This was especially true for PWH with CD4 counts <200 cells/μL (sky blue tree sections), in whom a median of 46 haplotypes/person (IQR 14–114/person) were detected over the course of infection." (PMID 38313289, 2024). "In early stages of infection, CD8+ T cells are distributed in a circular formation on the outer layer of the lymphocytic core, and with chronic infection, they become more interspersed with CD4+ T cells throughout the granuloma." (PMID 38165044, 2024). "For cell-free infection experiments, the progeny viruses produced from infected MDMs, with or without MARCH8 knockout, were normalized and used for cell-free infection of the HeLa-derived CD4-positive cell line MAGIC5." (PMID 38667313, 2024). "DP T cells derived from both CD4+ and CD8+ SP T cells expressed higher levels of Tax than their parent SP T cell populations, indicating higher rates of infection in the newly generated DP T cells and consistent with the increased ex vivo infection rate of DP T cells." (PMID 38193535, 2024). "All measured immune cells increase in median number per granuloma between day 56 and day 114, and this increase remained similar across B cells, CD4, and CD8 cells, but these changes between infection endpoints are small in comparison to the large variability observed within each group." (PMID 39253081, 2024). "Based on observations that HIV-specific CD4+ T-cell responses increase in PWHs receiving ART and ECs, it is argued that specific CD4+ T-cell responses initiated early in infection may be beneficial for disease outcome." (PMID 38932264, 2024). "However, the vaccines promote generation of helper CD4+ TCM, and they have been demonstrated to aid in the generation of pathogen-specific CD8+ memory T cells that can be activated by a secondary infection of the virus." (PMID 38675771, 2024). "SEA, through kappa‐5, can powerfully block dendritic cells DC‐SIGN mediated HIV‐1 trans‐infection of CD4+ T‐lymphocytes, nevertheless not block cis‐infection." (PMID 39560407, 2024). "CD4+ T cells play a critical role in macrophage activation through the production of IFN-γ, which directly enhances macrophage functionality to control the infection and facilitates the development of an effective antibody response." (PMID 39770852, 2024). "In a recent study measuring a limited panel of inflammatory biomarkers, we identified two common patterns of CSF biomarker changes as blood CD4+ T-cell declined during untreated infection in the absence of HAD." (PMID 39316609, 2024). "Six days post infection of CD4+ T cells with wild-type HIV-1NL4 − 3, antiretroviral compounds including AZT and lopinavir were added to the culture medium to suppress viral replication and prevent further spread of infection." (PMID 38468291, 2024). "Contrary to expectation, no cells were found with a CD4+ Th2 transcriptome profile, not even during the late stage of infection, which is hallmarked by increased plasma concentrations of IL-10." (PMID 38535532, 2024). "CD4+ T cells are critical for defense against Salmonella and several groups have shown that Salmonella specifically reduces the surface levels of MHC-II during infection, which negatively impacts CD4+ T cell generation." (PMID 38911854, 2024). "Overall, analysis of T cell representation in blood and CNS showed that after infection, T cells increased in blood with a greater increase in CD8 than CD4 T cells, while in the brain there was also a steady increase in T cells with more CD8 T cells early and CD4 T cells later." (PMID 38695564, 2024).
infection (continued). "In the absence of E2 treatment, mean CD4+ T cell infection frequency was again significantly greater in the EM of post-menopausal versus pre-menopausal women (6.3% versus 1.7%)." (PMID 39872519, 2024). "HIV-1 initially targets CCR5-expressing tissue memory CD4+ T cells, and in the absence of early cART initiation, a co-receptor switch may occur, leading to the infection of naïve and memory CXCR4-expressing CD4+ T cells." (PMID 38787201, 2024). "In contrast, in CD4+ T cells TGF-β is known to decrease TCR activation, restrict proliferation and inhibit cytotoxicity (including granzyme and perforin release) at different stage of infection in vivo." (PMID 38355731, 2024). "Notably, the number of DRIPc-seq peaks mapped to the human reference genome increased markedly during the early post-infection with HIV-1 (3 and 6 hpi for HeLa cells and 6 and 12 hpi for CD4+ and Jurkat T cells)." (PMID 39630854, 2024). "Tissue resident memory CD4+ and CD8+ T cells may make the decidua of HCMV seropositive women resistant to infection." (PMID 39495799, 2024). "Importantly, the adoptive transfer of mito‐transferred naïve CD4+ T cells from old mice into Rag1‐KO mice protected these mice against influenza A virus (IAV) and Mycobacterium tuberculosis (M.tb) infections." (PMID 37990641, 2024). "A study performed on Gulf Coast native lambs that were treated with mouse anti-ovine CD4+ monoclonal antibodies to experimentally reduce lymphocytes showed a higher number of parasite infections when compared to the non-depleted control group." (PMID 38338687, 2024). "As in the CD4+ cell depletion experiments, we tested whether MR1 administered through the second infection period impacted the initial and/or established lung B cell populations." (PMID 38715601, 2024). "To understand how the Fas-FasL pathway may influence the development of an antiviral response in spinal cord infection, we analyzed CD4+ T-cells, CD8+ T-cells, and NK cell counts by flow cytometry in spinal cord homogenates at two time points of infection." (PMID 39339840, 2024). "Immunological (CD4+ cells, CD8+ cells, and CD4+/CD8+), virological (plasmatic HIV viremia), serological parameters for several infections (presence of CMV IgG, HCV antibodies, HBsAg, HBcAb or Toxoplasma IgG), and the number of comorbidities did not appear to alter the risk of PCCs in our cohort." (PMID 38700658, 2024). "At day 2 post-Lpn infection, CD4+ TIA cells were still negative for CD103, confirming that they do not represent a tissue-resident memory population." (PMID 38838013, 2024). "CD4+ T cell counts begin to rise as expected in response to therapy, but patients who develop IRIS will additionally experience an excessive inflammatory response to prior infections, typically within 6 months of initiating HAART." (PMID 38474196, 2024). "Studies in mouse models have shown that B. pertussis infection or immunization with wP vaccines promote accumulation of B. pertussis-specific CD4 TRM cells in the lungs and nasal tissue and that these cells produce IFN-γ and IL-17 that mediate long-term protection against infection." (PMID 38290045, 2024). "Depletion of CD4+ cells just before the second Sp19F infection did not impact IV blood B cells but diminished EV lung B cells." (PMID 38715601, 2024). "The other animal, NV19, also experienced a decline in CD4+ T cells across all sampled compartments, and although its levels began to rebound, they never returned to pre-infection levels." (PMID 39066335, 2024). "Treatment of PPLHIV with biologic therapy does not significantly affect HIV viral load, CD4 cell count, CD4 proportion, and infection rate during the first 12 months of treatment." (PMID 39605044, 2024). "Additionally, there was a significant increase in both CD4 and CD8 T-cell populations at both early and late infection." (PMID 39483462, 2024).
infection (continued). "Patient 1 in this study had a CD4 T-cell count of less than 100 cells/ul, which is not an absolute contraindication of liver transplantation without an established infection." (PMID 38589801, 2024). "Two distinct T cell subpopulations, CD4+ and CD8+, play crucial roles during infections and complement the ability of the innate immune system to curb initial pathogen replication and cooperate with antibodies in preventing the infection of new cells." (PMID 39591183, 2024). "We found a correlation between bivalent vaccine-induced neutralizing antibodies and CD4 T cells among individuals without prior infection, and their levels were lower in those with subsequent breakthrough infection." (PMID 38594497, 2024). "We propose that CD40L signaling from antigen-stimulated CD4+ T cells in the infected lung is critical to establishment of local BRM cells, which subsequently protect the airways and parenchyma against future potential infections." (PMID 38715601, 2024). "Thus, we exposed baboon CD4 cells to 10-fold serial dilutions of maraviroc during SIVmac and SIVbn-PBMC P4 s1 infection." (PMID 39006742, 2024). "In the very early stages of infection (2 dpi), only rare single SIV-infected CD4+ T cells could be identified, though they were found to be present in both the rectum and the distal colon." (PMID 39641272, 2024). "Either by EBV primoinfection or infection by another pathogen that decreases CD4 T-cell responsiveness would increase the number of EBV-latent cells in different tissues, as EBV type I latent B cells are only controlled by EBNA-1-specific CD4 T cells." (PMID 39044822, 2024). "Analysis of CD69 and CD103 expression in the lung pre- and post-Lpn challenge revealed a lack of tissue residency marker expression among CD4+ TIA cells prior to the Lpn infection." (PMID 38838013, 2024). "The absence of IL-22 in CD4+ T cells results in an inability to restrain the proliferation of C. rodentium during the late phase of infection, leading to ~40% mortality." (PMID 39379604, 2024). "Interestingly, as shown in the lower left part of the correlation matrices, significant correlations between specific CD4+ and CD8+ T-cell populations were only found among individuals with prior infection." (PMID 38326340, 2024). "Specifically, in the mock-treated group, the percentage of CD8+ and CD4+ T cells amongst CD45 + cells was low with 3.4% and 8.9%, respectively, whereas under conditions of VSV-infection a profound increase of both CD8+ (96.7%) and CD4+ (91.1%) T cells was detected." (PMID 39153993, 2024). "The CCR5-expressing CD4+ T cells decreased by the peak of infection in the colonic LNs, as well, though without reaching significance (P > 0.1266)." (PMID 39641272, 2024). "In contrast, there was in increase in CD4+ lymphocyte % apoptosis (p = 0.0059) among pre-operative samples from patients with post-operative infections, but no increase in PD-1 expression." (PMID 38655251, 2024). "Although inbred and genetic knockout mice are easily available, and readily infected using Mtb, most strains of mice are not a natural host for HIV, which require human CD4+ T cells to establish infection." (PMID 38799434, 2024). "Before infection, we did not see a difference in CD4+ T cell numbers between vaccinated and unvaccinated groups." (PMID 38712080, 2024). "Previous studies have reported that guanine nucleotide peptides can stimulate the proliferation of existing CD4+ T cells and induce oligo-clonal TCR expansion, indicating that stress, inflammation, and/or infection can induce protein citrullination on CD4+ T cells." (PMID 38672418, 2024). "CSF lymphocyte analysis showed trend for CD4+ T cell reduction during the first 12 weeks of infection (not significant), while CD8+ T cells exhibited an increase (P < 0.05; fold change, 13)." (PMID 38470479, 2024).
infection (continued). "Intriguingly, while the proportion of IL-17-producing CCR6+ CD4+ T cells or TEMRA CD8+ T cells did not change by 28 days after infection, the proportion of IFN-γ-producing TEMRA CD8+ T cells declined by 28 days (P < .01)." (PMID 39008280, 2024). "Considering the significant activation and accumulation of CD4+ and CD8+ EM T cells, it is notable that only a small fraction of both subsets expressed any of these 3 cytokines during infection, demonstrating the exceptionally tight regulation of these potent immune signaling proteins." (PMID 38814732, 2024). "Although CD4+ T cells produce IL-10, which is important in promoting parasite survival, how such responses develop from precursors during infection is not known." (PMID 39201440, 2024). "Furthermore, favorable Th1-biased CD4+ and CD8+ T-cell responses elicited by mRNA-1647 were similar to or higher than those observed from natural infection with CMV." (PMID 38526054, 2024). "Future studies are needed to further evaluate the role of vaccine-induced neutralizing antibodies and CD4 T cells as indicator of protection in individuals with and without prior infection." (PMID 38594497, 2024). "CD4+ and CD8+ T cells, as well as cells of the innate immune response, such as macrophages, are deeply involved in disease outcome, as in the pattern of cytokines released during infection." (PMID 38410517, 2024). "We found that the CD4+ compartment was predominantly naive in all animals regardless of infection, although infants had somewhat lower CD4+ TN frequencies than newborns 6 weeks p.i.." (PMID 39190496, 2024). "Moreover, although the numbers of CD4 T cells in IAV-infected IkkαF/F and IkkαLyve-1 mice were similar between both groups at day 7 after infection, CD8 T cell numbers and frequency were significantly lower in IkkαLyve-1 lungs." (PMID 39007717, 2024). "When analyzing the whole group of individuals irrespective of prior infection, a correlation between CD4 T cells and IgG as well as neutralizing antibodies towards the parental strain and Omicron subvariant BA.2 and BA.4 was found." (PMID 38594497, 2024). "Moreover, although contracted CD4+ T cell population was found as the infection progressed (e.g., day 16 p.i.), RACK1 KO mice exhibited a persistently lower proportion and overall number of CD4+ T cells in the spleen, as compared with those in WT mice." (PMID 39024388, 2024). "The number and percentage of IFN-γ-secreting CD4 T cells in lung of EPS301-adjuvanted mice was significantly accumulated compared with non-vaccinated mice, but much below than CTB-adjuvanted mice on day 7 post vaccination in response to infection." (PMID 39556597, 2024). "Meanwhile, CD4+ T cells in the skin exhibit a more dynamic pattern of migration and recirculation than cutaneous CD8+ T cells that reside in the epidermis and are confined largely to the original site of infection." (PMID 38632596, 2024). "Among PLHIV with CD4+T lymphocyte counts less than 50 cells/μL, 14 individuals were found to have two or more pathogens (co-infections), 3 PLHIV patients exhibited single-pathogen infections, and only 1 patient showed pathogen negativity." (PMID 38774626, 2024). "Both CD4+ and CD8+ TRMs were predicted to be critical for the rapid elimination of infection." (PMID 39599904, 2024). "Increased numbers of CD4+, ɣδ+ T lymphocytes were found in the abomasal tissue 5 days after infection, with no further increases observed in the adult nematode infected group." (PMID 38338687, 2024). "In the testes, myeloid cells and CD4+ T cells were absent at 7 dpi but were present at 23 days post-infection (dpi), and CD8+ T cell infiltration started at 7 dpi." (PMID 40295722, 2024). "Notably, CTLA-4 expression was also increased in CD4+ CCR4+ CXCR3− TH2 and CD4+ CCCR6+ CCR4− CXCR3− TH9 at 8-weeks and 12-weeks post-infection, respectively." (PMID 39411786, 2024). "Activated CD4+ and CD8+ T cells play a pivotal role in clearing the primary infection." (PMID 38792338, 2024).